IL2 (interleukin 2)
Diseases named in the same sentence as IL2 in open-access papers (continued):
Sharing a sentence is not in itself a finding about the gene and the disease.
non-small cell lung carcinoma (45 papers, 1992 to 2025). A group of at least three distinct histological types of lung cancer, including non-small cell squamous cell carcinoma, adenocarcinoma, and large cell carcinoma. "Clinical research has revealed a significant correlation between IRF1 and the level of circulating IL-2, which is linked to the effectiveness and prognosis of chemotherapy for non-small cell lung cancer." (PMID 38915471, 2024). "Activation of CD3EAP may cause T cells to produce IL2 to play an important role in non-small cell lung cancer." (PMID 34026613, 2021). "The IL-2, combined with targeted therapies such as gefitinib, showed a positive response in non-small cell lung cancer (NSCLC) patients." (PMID 40670434, 2025). "Treatment for 16 individuals with advanced non-small cell lung cancer included low-dose interleukin-2 and tumor necrosis factor." (PMID 36874133, 2023). "One of the major phase III clinical trials used TG4010, a modified vaccinia Ankara vector expressing MUC1 and interleukin-2, in combination with chemotherapeutic drugs or placebo in 222 non-small cell lung cancer (NSCLC) patients." (PMID 36612133, 2022). "The vaccine TG4010, an MVA vector expressing MUC1 and IL-2, has been evaluated in 2 randomized clinical trials in combination with first-line chemotherapy for treatment of patients with advanced-stage non-small-cell lung cancer." (PMID 30626434, 2019). "Low levels of soluble PD-L2 and IL-2 and high levels of soluble IFN-γ were associated with grade 3/4 toxicities in non-small cell lung cancer treated with nivolumab." (PMID 31464648, 2019). "This is further demonstrated in patients with advanced non-small cell lung cancer in whom increased numbers of IFN-γ-producing PBMCs correlated with prolonged median survival time upon an administration of α-GalCer pulsed IL-2/GM-cultured PBMC." (PMID 26121617, 2015). "Safety and tolerability of ex vivo TKD/IL-2 stimulated, autologous NK cells has been demonstrated in patients with metastasized colorectal and non-small cell lung cancer (NSCLC) in a phase I clinical trial." (PMID 25926832, 2015). "In a randomized phase II clinical trial, we have shown previously that the adoptive transfer of ex vivo Hsp70-peptide TKD and IL-2-activated autologous (patient-derived) NK cells provides a survival benefit in patients with advanced non-small-cell lung carcinoma." (PMID 38137456, 2023). "Intrapleural IL-2 was well tolerated in non-small cell lung cancer (NSCLC)." (PMID 30999958, 2019). "Similarly, patients with non-small cell lung cancer (NSCLC) display higher levels of IL-2 as compared to healthy controls." (PMID 31827925, 2019). "Based on these findings, a phase II clinical trial was initiated with the goal to determine the efficacy of ex vivo HSP70 peptide plus IL-2 stimulated autologous NK cells in patients with inoperable non-small cell lung cancer (NSCLC) in stage IIIA/B after radiochemotherapy." (PMID 29203711, 2018). "Advanced non-small cell lung cancer patients receiving TG4010, a therapeutic viral vaccine encoding human Mucin 1 and interleukin-2 in addition to standard chemotherapy, displayed longer overall survival in comparison to that of patients treated with standard chemotherapy alone." (PMID 28923084, 2017). "A previous study focused on non-small-cell lung cancer also similarly found that CXCR5+ Tfc-like cells rapidly gained a polyfunctional effector phenotype by producing the cytokines TNF-α, IFN-γ, and IL-2 after hours of PMA/ionomycin stimulation." (PMID 35443611, 2022). "It has been reported that IL-2 and IFN-γ in plasma increase significantly in patients with non-small cell lung cancer, 1 month after microwave ablation." (PMID 36497106, 2022).
non-small cell lung carcinoma (continued). "It has been reported that unfractionated self-peripheral blood mononuclear cells (PBMC) can be co-cultured for a long time with epithelial cell organoids from CRC or non-small cell lung carcinoma (NSCLC) in the presence of IL2, IFNγ, anti-CD3 and anti-CD28 antibodies coated to plastic for 28 days." (PMID 34298630, 2021). "Exosomes isolated from non-small-cell lung cancer (NSCLC) patients reduced IFNγ and IL-2 production and induced apoptosis in CD8+ T cells, favoring tumor growth." (PMID 34065396, 2021). "The PD-L1 expressing human non-small cell lung cancer cell line, NCI-H2023 was co-cultured with human CD3+ T cells that were stimulated for 2 days with suboptimal concentrations of CD3, CD28, and IL2." (PMID 30563566, 2018). "A phase I clinical study involving eleven patients with metastatic colorectal cancer and one patient with non-small cell lung cancer (NSCLC) has shown that the re-infusion of autologous, TKD/IL-2-activated leukapheresis products is feasible, safe and well-tolerated." (PMID 19549307, 2009). "By contrast, pro-inflammatory Th1 cytokines including IL-2, TNF-α, IFN-γ had not noticeably altered, consistently with the study in malignant pleural effusion of non-small cell lung cancer." (PMID 37215450, 2023). "Finally, in 2 studies of non-small cell lung cancer (NSCLC) involving 10 and 15 patients, respectively, who received ex vivo-expanded Vγ9Vδ2 T cells and IL-2, there were no objective clinical responses although about one-third to one-half of the patients showed stable disease after therapy." (PMID 29163482, 2017).
Stroke (45 papers, 2011 to 2026). Sudden impairment of blood flow to a part of the brain due to occlusion or rupture of an artery to the brain. "Our study confirmed that intraperitoneal injection of the IL‐2:IL‐2 Ab complex after stroke increased the amount of Tregs on the 14th day after stroke and reduced neuronal death and myelin loss in the brain tissue on day 21 after stroke." (PMID 41552852, 2026). "Particularly, heightened levels of IL-2 were positively correlated with the presence of multiple risk factors in stroke patients (P < 0.001, χ2 = 27.701)." (PMID 38287458, 2024). "In contrast to precedent investigations, our research unearthed a distinctive immune response among stroke patients grappling with one or more risk factors, characterized by diminished levels of various helper T cell 1 (Th1)/Th2 factors in their plasma, except for elevated IL-2 levels." (PMID 38287458, 2024). "Remarkably, the current study demonstrated that IL-2/IL-2Ab treatment of Tregs suppressed the detrimental inflammatory response associated with cell death, supporting the application of Tregs in conjunction with IL- IL-2/IL-2R to curtail secondary cell death after stroke." (PMID 33830475, 2021). "Flow cytometry analysis showed that compared with the MCAO + IgG group, the ratio of CD4+CD25+Foxp3+ Tregs increased significantly in the MCAO + IL‐2:IL‐2 Ab group on the 14th day after stroke." (PMID 41552852, 2026). "It has been demonstrated that increasing the number of Tregs by pretreatment with the IL‐2:IL‐2 Ab complex can enhance Treg‐mediated responses and ameliorate ischemic brain injury in the acute phase after stroke." (PMID 41552852, 2026). "Pro-inflammatory cytokines like IL-1β, IL-2, and IL-6 are typically found at low levels in the brain, but their levels increase following a stroke." (PMID 40292265, 2025). "This dysregulation led to hyperactivated T cells, higher levels of cytokines (IL-2, IL-6, IL-10, IFN-γ), and an increased risk of stroke." (PMID 41156185, 2025). "IL-2, by stimulating T cell activation and proliferation, regulates the immune response after stroke and influences the differentiation of TH1/TH2 cells and related factors, thereby modulating the immune response." (PMID 38742047, 2024). "Specifically, elevated levels of LDL, HDL, and IL-2 were positively linked to the presence of comorbid hypertension in stroke patients (LDL: P = 0.040, χ2 = 5.068; HDL: P = 0.006, χ2 = 7.658; IL-2: P < 0.001, χ2 = 21.879)." (PMID 38287458, 2024). "Studies have shown that serum levels of IL-6, IL-5, IL-10, and IL-2 in stroke patients are closely correlated with stroke prognosis." (PMID 38742047, 2024). "Increasing the number of Treg cells by overexpressing IL-2 in the IL-2:IL-2 antibody complex or astrocytes after stroke restores neurological function in the long term." (PMID 38824594, 2024). "They observed IL-2 secretion by astrocytes and its protective effects on the nervous system in mouse models of traumatic brain injury, stroke, and MS." (PMID 38455364, 2024). "The only previous report of cytokine measurement in CSF from dogs with naturally occurring stroke assessed for IL-2, IL-6, IL-8, and TNF." (PMID 37266378, 2023). "This suggests that unfavorable kinetics of IL-2 production preclude efficacy during the rapid damage that occurs following stroke." (PMID 35618831, 2022). "Increasing the levels of IL-2 and IL-2 antibody complexes after stroke can increase the number of regulatory T cells, which can improve white matter integrity in the long term and protect nerve functions." (PMID 35656537, 2022). "In this context, treatment with IL-2 following the primary stroke resulted in significant reduction of lesion size in the secondary stroke." (PMID 35618831, 2022). "After stroke, increasing Treg cell numbers by delivering IL-2:IL-2 antibody complexes can improve white matter integrity and rescue neurological functions over the long term." (PMID 35173738, 2022).
Stroke (continued). "The findings identified that IL-2, IL-6, IL-10, and IFN-γ were risk factors for stroke risk in AF patients (P < 0.05)." (PMID 35600045, 2022). "It was shown that IL-2 administration improves the resolution of the stroke, by controlling the T-reg levels." (PMID 36080256, 2022). "IL-2 has been shown to be necessary for Treg expansion following stroke recovery and its provision limits EAE-induced disease activity." (PMID 34631704, 2021). "After stroke, the number of Treg cells was increased by the delivery of IL-2: IL-2 antibody complex, which improved the integrity of white matter and saved nerve function for a long time." (PMID 34335600, 2021). "After a stroke, increasing the number of Tregs by delivering an IL-2:IL-2 antibody complex can improve the integrity of white matter and save neurological function for a long time." (PMID 34490267, 2021). "The treatment of IL-2/IL-2R in mice significantly improves stroke outcomes, elevates Treg numbers, and increases the function and expression of CD39 and CD73." (PMID 33830475, 2021). "While boosting Treg cell number by administration of IL-2:IL-2 antibody complexes markedly improved white matter integrity and long-term stroke outcomes." (PMID 34881289, 2021). "The present study probed to delineate the direct effects of IL-2/IL-2R complex from Tregs in the in vitro stroke model of oxygen glucose deprivation/reoxygenation (OGD/R) model." (PMID 33830475, 2021). "Altogether, these data showed that IL-2/IL-2R-treated Tregs alleviated the injured neurovascular unit (NVU) following stroke by attenuating the inflammation-plagued secondary cell death." (PMID 33830475, 2021). "The present in vitro study showed that IL-2/IL-2R antibody complex facilitates Treg-induced neuroprotection in the oxygen glucose deprivation/reoxygenation (OGD/R) model of stroke." (PMID 33830475, 2021). "Treatment with IL-2/IL-2R complex reduces stroke-induced inflammation and neurological deficits, coincident with increased Tregs in vivo." (PMID 33830475, 2021). "Altogether, these observations support the use of IL-2/IL-2R treatment in enhancing the anti-inflammatory effects of Tregs in stroke." (PMID 33830475, 2021). "Although IL-2 is one of the most frequently studied cytokines in stroke patients, the conclusions are ambiguous and inconsistent with the results of experimental studies." (PMID 32795376, 2020). "As markers and mediators of systemic inflammation, increases in inflammatory cytokines, such as interleukin (IL)-2, IL-6, myeloperoxidase, and integrins, are abundant in polymorphonuclear neutrophils and are related to oxidative stress after a stroke." (PMID 32231119, 2020). "In BALB/c mice at 7 weeks post-stroke, levels of G-CSF, IL-2, IL-6, IL-17, IP-10, MCP-1, and RANTES were increased, and levels of GM-CSF, IFNγ, IL-10 were decreased compared to sham mice." (PMID 27600707, 2016). "In addition, the expression of synaptic plasticity‐associated proteins Synaptophysin, PSD95 and GAP43 in the hippocampus was significantly decreased following stroke, which were upregulated by IL‐2:IL‐2 Ab complex and inhibited by 4‐CIN." (PMID 41552852, 2026). "Furthermore, we observed noteworthy disparities in the plasma levels of IL-2, IL-4, IL-6, IL-10, TNF-α, and INF-γ between patients devoid of risk factors and those presenting with comorbid risk factors associated with stroke." (PMID 38287458, 2024). "In stroke models, beneficial effects have been shown with direct Treg cell therapy (although this only works in Rag‐deficient mice), or via the use of IL33 or IL2 to expand the Treg population." (PMID 36975362, 2023). "Additionally, IL-10 inhibits IL-2 activity, and has been shown in numerous studies to be increased after stroke or TBI." (PMID 35745576, 2022). "Even in stroke, with a narrow treatment window, a lasting gene delivery of IL-2 may have clinical benefit; 10% of stroke patients experience a secondary stroke within 90 d41." (PMID 35618831, 2022).
Stroke (continued). "IL-2 levels were significantly higher in the group treated with 0.5mg/mL Compound 4, which supports our hypothesis, that Compound 4 is beneficial for stroke management." (PMID 36080256, 2022). "IL-2/IL-2R treatment mitigates brain infarct and recovers motor functions after stroke." (PMID 33830475, 2021). "Because both microglia and glia have been recognized as not merely by-stander or supporting cells of the neurovascular unit, thus they participate closely in stroke pathology and treatment, an in-depth examination of their active roles in IL-2 and Tregs neurovascular protection is warranted." (PMID 33830475, 2021). "Furthermore, treatment with IL-2/IL-2AB decreased brain infarction and enhanced neurological outcomes in a rat model of stroke." (PMID 34073791, 2021). "The concept of IL-2/IL-2R complex-mediated Treg approach represents a novel stroke treatment in that it affords a wider therapeutic window, recapitulates a pharmacologic ligand–receptor interaction, and acts by regulating the inflammation-plagued secondary cell death." (PMID 33830475, 2021). "In the memory stage, the experimental results revealed that mice in the MCAO + IL‐2:IL‐2 Ab group stayed longer in the target zone compared with the MCAO + IgG group, suggesting that Tregs could alleviate spatial memory impairment caused by stroke." (PMID 41552852, 2026). "Previous research has showed that IL-2/IL-2Ab treatment selectively increases the amount of Tregs in the lymph nodes, spleen, and blood, significantly reduces the infarct volume, inhibits neuroinflammation, and improves sensorimotor function compared to stroke mice treated with isotype IgG." (PMID 35173738, 2022). "Increasing the number of Treg cells by administering IL-2:IL-2 antibody complexes after stroke improved the white matter status and restored neurological function in the long-term, suggesting that Tregs could be a therapeutic target of neural recovery after stroke." (PMID 35911740, 2022). "In this study, we demonstrated that administration of the IL‐2:IL‐2 Ab complex at 6 h after MCAO expanded the number of Tregs and improved long‐term neurological recovery in stroke mice." (PMID 41552852, 2026). "In our study, the salivary concentration of IL-2, IL-5, IL-7, IL-10, IL-12 (p70), IL-13, IL-15, and IFN-α2 was below the detection level in healthy controls (most commonly) and in stroke patients." (PMID 40520895, 2025). "Inflammatory response was determined by detecting levels of cytokines (interleukin-2 [IL-2], IL-4, IL-5, IL-8, IL-6, IL-10, IL-12p70, IL-17, tumor necrosis factor-α [TNF-α], interferon-γ [IFN-γ], IFN-α, and IL-1β) within 14 days after stroke onset." (PMID 38902691, 2024). "Levels of TNF-α, TNF-γ, IL-6, MCP-1, and IL-2 were significantly increased at 6 and 22 h after MCAO in mice with stroke injuries." (PMID 39081338, 2024). "Recognizing the multiple cell types in the neurovascular unit, we next tested the role of IL-2/IL-2R in OGD/R-exposed NPCs, which recapitulated both ischemic gray and white matter damage in the stroke brain." (PMID 33830475, 2021). "First, we examined the role of IL-2/IL-2R-treated Tregs in OGD/R-exposed rat primary cortical cells (PCCs), which represent the cell type of the ischemic gray matter in the stroke brain." (PMID 33830475, 2021). "Second, we next assessed IL-2/IL-2R effects in OGD/R-exposed human oligodendrocyte progenitor cells (OPCs), which correspond to the white matter injury after stroke." (PMID 33830475, 2021). "In stroke, other Treg-modulating therapies, including CD28 superagonist, IL-33, IL-2/IL-2-antibody complex, and adoptive Treg cell transfer, have been shown to increase peripheral Treg frequencies by two- to three-fold in young mice." (PMID 33516262, 2021). "The expansion of Tregs via IL-2/IL-2 antibody complexes and brain-targeted IL-2 overexpression in astrocytes via AAV vectors have shown beneficial effects in MCAO and cortical impact mouse models of stroke." (PMID 40804450, 2025).
Stroke (continued). "Between the two groups,there were statistically significant differences in age, hypertension, previous strokes, WBC, neutrophil, monocyte, eosinophil, albumin, BUN, Cr, free IL-2, IgA, IgG, CRP, C4 (p < 0.05), and the other factors were not significantly different (p > 0.05)." (PMID 38887608, 2024). "The equilibrium of Th1/Th2 cytokines holds paramount importance in the genesis and progression of stroke, wherein post-stroke imbalances tend to favor Th1-type responses—inclusive of IFN-γ, TNF-α, and IL-2—potentiating the exacerbation of cerebral damage and neurologic deficits." (PMID 38287458, 2024). "The therapeutic potential of this is not unrecognized – IL-2/IL-2c complexes, which selectively expand Treg populations, are protective in models of stroke and traumatic brain injury." (PMID 34631704, 2021). "The role of IL-2/IL-2R in facilitating Treg-induced neuroprotection was initially explored in OGD/R-exposed PCCs, which represented the cell type of the ischemic gray matter in the stroke brain." (PMID 33830475, 2021). "The contribution of IL-2/IL-2R to Tregs’ neuroprotection was next explored in OGD/R-exposed OPCs, which corresponded to the cell type found within the ischemic white matter in the stroke brain." (PMID 33830475, 2021). "Thus, we investigate the role of an IL‐2 monoclonal antibody (IL‐2mAb, JES6‐1) in combatting demyelination during the late phase of stroke." (PMID 30444079, 2019). "Compared to 7 days after stroke, the levels of OPC markers at 14 days were not significantly changed between IgG and IL‐2 treated groups." (PMID 30444079, 2019). "In stroke patients, rehabilitative 4-week treatment with ELF-EMF (F = 40 Hz, Bm = 5 mT), in combination with physiotherapy, reduced both IL-1β plasma and IL-1β mRNA expression levels and increased IL-2 plasma levels without any adverse effects." (PMID 35203533, 2022).